MTAP (methylthioadenosine phosphorylase)
Diseases named in the same sentence as MTAP in open-access papers (continued):
Sharing a sentence is not in itself a finding about the gene and the disease.
tumor (continued). "The discrepancy between MTAP-mediated cell proliferating ability in vitro and in vivo indicated that MTAP may contribute to the BC tumor growth by regulating the tumor microenvironment." (PMID 35541910, 2022). "Therefore, it is possible that the influence of MTAP on angiogenesis also plays a significant role in BC tumor growth and metastasis." (PMID 35541910, 2022). "We then sacrificed the mice at 24 days post-injection to investigate whether MTAP was involved in the tumor growth and metastasis." (PMID 35541910, 2022). "Both in vitro and in vivo assays were used to investigate the tumor suppressive function of MTAP." (PMID 35541910, 2022). "In tumors in vivo, MTAP− tumor cells are often in close proximity to MTAP+ stromal cells." (PMID 35963436, 2022). "Notably, aberrant expression of three proteins among these has been highlighted as being involved in cell proliferation and tumour growth, in particular MTAP down-regulation." (PMID 34795367, 2021). "Owing to the proximity of MTAP to the CDKN2A tumor-suppressor locus, co-deletion of MTAP may be observed in 80–90% of all tumors harboring homozygous deletion of CDKN2A8." (PMID 34244484, 2021). "In the present study, MTAP expression was performed in tumor sections biopsied from metastatic lung adenocarcinoma patients initially treated with pemetrexed-platinum chemotherapy plus bevacizumab to explore the correlation of its expression and clinical outcomes." (PMID 31965001, 2020). "Out of the other seven discordant MTAP only cases, three cases (190075, 190081, and 190099) were attributed to tumor heterogeneity, three cases (190106, 190118, 190120) were due to marginal ddPCR count threshold and one case (190043) was due to marginal FISH count threshold." (PMID 33304846, 2020). "The tumor suppressor roles of MTAP uncovered here was in line with multiple previous reports." (PMID 33155773, 2020). "Inhibition of MTAP decreased the level of adenine in A549 MTAP−/− xenograft tumor significantly compared that in H358 MTAP+/+ model; moreover, the tumor growth in A549 MTAP−/− xenograft mice was also inhibited dramatically by MTAP inhibitor in contrast to untreated mice." (PMID 31965001, 2020). "Subsequent comparisons of genomic profiles from an additional twelve LGSC cell models showed frequent deletion of Chr9p (including loss of MTAP and CDKN2A genes) and oncogenic mutations in KRAS and NRAS genes, in agreement with results from previous studies on LGSC tumor tissues." (PMID 30636931, 2019). "Interestingly, five genes with concordance between CNLs and down-regulation were observed in more than 50 tumor samples, including MTAP (216 samples), PTEN (143 samples), MCPH1 (86 samples), SMAD4 (63 samples), and MINPP1 (51 samples)." (PMID 27929028, 2016). "The MTAP gene wasreported to be capable of acting as a tumor growth suppressor." (PMID 26483964, 2015). "We characterized methylthioadenosine phosphorylase (MTAP) on 9p21.3 because whether the tumor-suppressive role of this polyamine metabolism-regulating enzyme is independent from the frequently co-deleted CDKN2A and CDKN2B genes still remains debated." (PMID 25426549, 2014). "The inhibiting effects of MTAP expression on tumor growth, angiogenesis, and the induction of apoptosis by L-alanosine were validated using MTAP-reexpressing xenografts and reverted using RNA interference in MTAP-preserved cells." (PMID 25426549, 2014). "We performed several assays to examine the effects of MTAP expression on tumor-related phenotypes." (PMID 25387827, 2014). "Until recently, scholars have started noticing the tumor-suppressive attributes of MTAP that may independently inhibit carcinogenesis." (PMID 25426549, 2014). "Co-deletion of the MTAP gene was observed in 1/9 (11%) cell lines and 3/42 (7%) tumours." (PMID 17533400, 2007). "All other tumours had immuno-detectable levels of MTAP protein expression." (PMID 15305192, 2004).
tumor (continued). "The underlying mechanism is by MTDIA causing accumulation of MTA in tissues regardless of tumor MTAP genotype due to the loss of MTA catabolism in all cells, thereby enhancing the MTA:SAM ratio, inhibiting PRMT5 activity, and providing dose-dependent sensitivity to MAT2a inhibitors." (PMID 38000655, 2024). "Iba‐1‐positive cells surrounding MTAP‐deficient cells normally expressed MTAP, implying that MTA synthesized by MTAP‐deficient tumor cells might be metabolized by normal cells in the brain, and these findings were the same across patients of different ages, gender, and disease processes." (PMID 39711357, 2024). "Also, in gross slides of WT cases, small groups of p16-MTAP-negative tumor cells could be identified between aggregates expressing both p16 and MTAP." (PMID 37894345, 2023). "According to several studies, MTAP-negative tumor cells are up to 20 times more susceptible to purine biosynthesis inhibitors such as MTX, 6-mercaptopurine, azaserine (a powerful inhibitor of the first step in purine biosynthesis), and L-alanosine, than MTAP-positive cells are." (PMID 36913304, 2023). "With or without MTAP loss, overexpression of PRMTs may represent a targetable vulnerability in many tumor types." (PMID 37237172, 2023). "Additionally, some tumor types with frequent MTAP gene deletion were included in part 1, but MTAP loss was not required for enrollment." (PMID 37237172, 2023). "In this work, we test our hypothesis and analyze tumor tissues for MTAP expression status in correlation with clinical responses to pemetrexed in patients with metastatic UC who either enrolled on our phase II clinical trial (NCT02693717) or were historically treated with pemetrexed." (PMID 35379845, 2022). "Similarly, pathway enrichment results revealed a marked involvement in the JAK–STAT, interferon, and mTOR signaling pathways, suggesting that MTAP/CDKN2AMUT may activate the anti-tumor immune response in the TME of RCC." (PMID 35979371, 2022). "We speculate that given the abundance of tumor-associated macrophages and the characteristic immunosuppressive microenvironment of GBM, altering MTA-mediated purinergic signaling has the potential to significantly impact tumor growth and augment immunotherapeutic interventions in MTAP-deleted GBM." (PMID 35264604, 2022). "We stratified CDKN2A/MTAP expression into increasing quartiles and first examined whether changes in CDKN2A/MTAP expression were associated with TME immune cell composition, PD-L1 expression on immune and tumor cells and the immune phenotypes." (PMID 34556668, 2021). "Additionally, MTAP rescue studies in xenografts suggest MTAP is a tumor suppressor." (PMID 29164057, 2017). "Therefore, study of MTAP may bring new insight to understanding the tumorigenesis and tumor-selective therapy." (PMID 29212228, 2017). "However, there is now substantial evidence that MTAP itself has tumor suppressor activity." (PMID 25387827, 2014). "Although superficially this seems to contradict the idea that loss of MTAP promotes tumorigenesis, it is important to remember that the drug may be exerting its antitumor effects not on the tumor directly but indirectly via its effects on stromal cells." (PMID 25387827, 2014). "Finally, we injected M+ and M− cells expressing a ZsGreen1 protein tag (see the section Materials and Methods) into SCID mice to determine whether MTAP expression could affect tumor cell growth in a mouse xenograft model." (PMID 25387827, 2014). "Interestingly, it has been shown that MTAP can be lost independently of CDKN2A, which suggests that loss of MTAP may indeed play a role in tumor biology." (PMID 23029397, 2012). "Unlike p16, which may demonstrate patchy or mosaic expression, MTAP loss tends to follow a binary pattern of either complete cytoplasmic absence or retention in tumor cells, accompanied by intact staining in internal non-neoplastic controls such as stromal fibroblasts or inflammatory infiltrates." (PMID 41596618, 2026).
tumor (continued). "Melanocytic tumorigenesis is deeply influenced by recurrent genetic alterations involving chromosome 9p21, a critical region that harbors key tumor suppressor genes, most notably CDKN2A and MTAP." (PMID 41596618, 2026). "Sequencing failed for 50 samples, leaving an initial cohort of 508 GI cancer patients to be screened for MTAP alterations (329 CRC, 80 PC, 47 GEC, 36 BTC, 16 small bowel or other tumours)." (PMID 38350716, 2025). "Following this line, the joined inhibition of MTAP and MAT2A promotes lethality in tumor models of CRC by reducing SAMe availability and increasing MTA level, thus rising MTA/SAMe ratio and inhibiting PRMT5 activity." (PMID 39941901, 2025). "Two additional scenarios were to model the preoperative situation as accurately as possible: Scenario 3 included MTAP expression, preoperative PSA, clinical tumor stage (cT stage) and Gleason grade obtained on the prostatectomy specimen." (PMID 40554389, 2025). "Although MTA-cooperative PRMT5 inhibitors have shown extensive potential in multiple MTAP-null preclinical models, questions have been raised about the presumed accumulation of MTA in the presence of the tumor microenvironment." (PMID 41439984, 2025). "Through genomics and transcriptomics analyses, we identify a subgroup of OS with methylthioadenosine phosphorylase (MTAP) deletion, which contributes to ICT resistance, leading to a “cold” tumor microenvironment." (PMID 39983717, 2025). "Low MTAP expression led to increased ODC activity and perturbations in polyamine metabolism, further affecting the growth and metastasis of tumor cells." (PMID 41439984, 2025). "TNG908 treatment maintainsstrong tumor control in the OCI-LY19 MTAP-null DLBCL xenograft model,but there is a slow tumor regrowth after a tumor volume nadir at 24days of treatment." (PMID 40035511, 2025). "TMA spots were informative for MTAP IHC in 385 (73.3%) and for MTAP FISH in 258 (49.1%) of the 525 arrayed tumor samples." (PMID 40664803, 2025). "Hemizygous MTAP loss was present in 5 of 38 (13.2%) cases, while in 5 (13.2%) cases MTAP deletion status could not be confidently interpreted, likely due to a combination of MTAP deletion sizes under the resolution of the CMA gene region probe coverage or lower tumor content." (PMID 39042515, 2024). "In our data, it is confirmed that the subcutaneous tumor established by Hs683 has less expression of MTAP and hardly affects the expression of PRMT5 compared with the mixed subcutaneous tumor inoculated with Hs683 and HMC3." (PMID 39711357, 2024). "Although thoracoscopic pleural biopsies that reveal tumor involvement of fat aid pathologists in making a diagnosis, utilizing BAP1/MTAP/CDKTA tests can potentially confirm the diagnosis, even without evident invasion." (PMID 38730667, 2024). "When MTAP‐deleted U‐118MG and Hs683 cells were co‐cultured with MTAP‐WT neuronal or microglia cells, the effect of MRTX1719 in inhibiting tumor cell proliferation was weakened significantly, and the lethality of normal brain cells was significantly enhanced." (PMID 39711357, 2024). "Further analysis of individual spots revealed a significant positive correlation between tumor infiltration by NK cells (CD56+) and average BAP1, NF2, MTAP, and LAG3 expression levels in MPM (ρ > 0.4)." (PMID 38994676, 2024). "MTAP gene is located at 9P21 surrounded by miR-31 and CDK2NA and has been reported to serve as a tumor suppressor gene." (PMID 36913304, 2023). "Topographic labeling of both MTAP and p16 in the same tumor areas of cases with a heterogeneous staining pattern indicates a common mechanism of inactivation of CDKN2A and MTAP genes." (PMID 37894345, 2023). "In MTAP null tumors, inhibition of Met adenosine transferase 2A (MAT2A) inhibits Met synthesis of SAM, thereby inhibiting tumor growth." (PMID 37699892, 2023). "CDKN2A is a tumor suppressor gene located on the chromosomal region 9p21 along with CDKN2B and Methylthioadenosine phosphorylase (MTAP) gene." (PMID 36362209, 2022).
tumor (continued). "Functional enrichment suggested that MTAP/CDKN2AMUT response genes participate in the aggregation and activation of immune cells in the tumor microenvironment (TME)." (PMID 35979371, 2022). "This study suggests that MTAP loss in GBM cells may contribute to the immunosuppressive tumor microenvironment, and that MTAP status should be considered for characterizing GBM immune states and devising immunotherapy-based approaches for treating MTAP-null GBM." (PMID 35264604, 2022). "Through phenotypic analysis, favorable clinical response to ICTs, elevated expression of immune checkpoints, increased abundance of tumor-infiltrated lymphocyte infiltration, and elevated TMB and PD-L1 expression were observed in the MTAP/CDKN2AMUT cluster." (PMID 35979371, 2022). "Moreover, although MTAP/CDKN2AMUT RCC may be insensitive to targeted therapy, the high degree of tumor heterogeneity and higher PD-L1 and CXCL13 expression characterizations reflected that MTAP/CDKN2A-deficient features could benefit from immunotherapy for patients with RCC." (PMID 35979371, 2022). "IBA1 levels in MTAP-deleted tumors nicely correlate with residual MTAP levels—i.e., the homozygous MTAP-deleted HF3174 tumor has the lowest IBA1 compared to other homozygous MTAP-deleted tumors, which also expresses the lowest but non-zero MTAP levels." (PMID 34244484, 2021). "While only subtle changes (vs. wild type) were observed in mRNA expression of CDKN2A/MTAP in 9p21-LOH tumors, homologous deletion of the genes in tumor cells led to a marked decrease in their mean gene expression levels in bulk tumor tissues." (PMID 34556668, 2021). "We stained a subset of 28 tumours with antibodies against BAP1 and MTAP (as a potential surrogate marker for CDKN2A deletion) along with PD-L1, VISTA, Ki-67 and an antibody for mitotic count." (PMID 34580349, 2021). "Clonal homozygous deletion involving the region 9p21.3, which harbours the tumour suppressors cyclin-dependent kinase inhibitor 2A and B (CDKN2A/B) and methylthioadenosine phosphorylase (MTAP), was found in seven patients (32%)." (PMID 33741915, 2021). "We also found 9p- deletion in approximately 50% of GBMs, affecting primarily the 9p21 locus where several tumor suppressor genes are located, including CDKN2A/B and MTAP." (PMID 32093414, 2020). "Chromosome 9p21.3 resides in a region distant from known coding regions, with tumor suppressor genes of cyclin-dependent kinase inhibitors (CDKN2A and CDKN2B) and methylthioadenosine phosphorylase." (PMID 30921371, 2019). "A decrease in MTAP expression was observed in RCC tissues and correlated with higher tumor grade and shorter overall survival." (PMID 30701095, 2019). "The methylthioadenosine phosphorylase (MTAP) gene is located at 9p21 and is flanked by the tumor suppressor miR-31 and the cyclin-dependent kinase inhibitor 2A (CDKN2A) gene, which are approximately 100 kb away." (PMID 26751376, 2016). "No significant change was detected for CDKN2A/p16INK4a, CDKN2A/p14ARF,CDKN2B/p15INK4b, MTAP, IFNA and IFNB mRNAs in tumours with 9p21–23 LOH when compared to those with retained heterozygosity." (PMID 15305192, 2004). "Approximately 70% of tumours in our series displaying 9p21–23 LOH had a SRO at a region telomeric to the CDKN2A and MTAP genes, near the IFNA and IFNB genes cluster." (PMID 15305192, 2004). "This was a stage 4 NB tumour (case #2) in which LOH was detected for microsatellites D9S319, D9S171 and D9S1752, a region centromeric to the MTAP gene." (PMID 15305192, 2004). "Multiple studies across tumor types have reported specificity values approaching or reaching 97–100% for homozygous 9p21 deletion when MTAP expression is absent." (PMID 41596618, 2026). "In contrast, BMS-986504 demonstrated minimal effects in tumor xenografts or hematopoietic cells without MTAP deletion." (PMID 41465382, 2025).
tumor (continued). "Indeed, single agent TNG462 was able todrive tumor regressions, including a complete response, in xenograftmodels representing multiple tumor types, demonstrating the potentialfor TNG462 to drive meaningful clinical responses in MTAP-deleted solid tumors." (PMID 40035511, 2025). "To evaluate whetherthe TNG462 antitumor activitywas limited by tumor histology, we also profiled TNG462 in a panel of 22 MTAP-null patient-derived xenograft (PDX) modelsrepresenting tumor histologies that are frequently MTAP-deleted." (PMID 40035511, 2025). "A greater reduction in tumor volume was seen in patients with CDKN2A and S-methyl-5’-thioadenosine Phosphorylase (MTAP) codeletions, which may suggest a greater clinical benefit in this subset." (PMID 41375064, 2025). "Our CNV analysis of various cell subpopulations showed that not all malignant tumor cell subpopulations exhibited MTAP deletion, highlighting the complexity of the TME." (PMID 39983717, 2025). "Non-informative cases (n = 4,558; 25.7 %) lacked MTAP staining on both tumor and stromal cells (IHC), unequivocal tumor cells on the TMA spots, or entire tissue spots on the TMAs." (PMID 40554389, 2025). "Following this, inhibition of glycolysis using 2-deoxy-D-glucose (2-DG) significantly reduced tumor growth in MTAP-KO preclinical models without significant inhibition in MTAP-WT models." (PMID 41439984, 2025). "Conversely, among the 12 cases lacking CDKN2A HD, cytoplasmic expression of MTAP in at least 1% of tumour cells was observed in 9 cases, whereas 3 resulted completely negative." (PMID 40566743, 2025). "Having identified MTAP‐WT cells' presence inside MTAP‐deleted tumors, we sought to investigate whether the PRMT5/MTA composition inhibitor played an ideal role in the tumor environment." (PMID 39711357, 2024). "We also found that NPC268 consistently harbors CN losses in three chromosomal arms in both tumor and cell line, including the 9p21.3 co-deletion of CDKN2A and MTAP which is a common event in NPC, implying that NPC268 could be vulnerable to MAT2A inhibitors." (PMID 38358347, 2024). "CDKN2A HD was absent in tumor areas where MTAP expression was preserved and CDKN2A HD was observed in tumor cells with MTAP loss." (PMID 38109891, 2024). "In one case with a homozygous deletion of both CDKN2A and MTAP and one case with a homozygous CDKN2A deletion and heterozygous MTAP deletion, strong MTAP expression was seen in 10% of the tumor cells, whereas p16 was negative in both cases." (PMID 37894345, 2023). "The tumor showed EGFR C797S, T790M, exon 19 deletion (T751_I759>N), CDK4 amplification, MDM2 amplification, CDKN2A/B loss, MTAP loss, low MSI, low TMB and negative PD-L1." (PMID 38111812, 2023). "In a xenograft study of HCT116 MTAP-negative tumours AG-270 resulted in 75% growth inhibition, while treatment with compound 28 led to complete tumour stasis." (PMID 37795443, 2023). "Therefore, to determine which of these events contributed to the oncogenic effects of MTAP-ANRIL, we investigated the MAPK and Akt signaling pathways, which play key roles in tumor proliferation and metastasis." (PMID 37277447, 2023). "Inhibiting MAT2A and reducing SAM levels has been proposed to cause PRMT5 inhibition both by removing its substrate and, in the case of MTAP-negative tumours, by providing a greater opportunity for MTA binding." (PMID 37795443, 2023). "The other molecules, including IFN-γ, CXCL, CTLA-4, MTAP, SFR4/CPXM1/COL5A1, TILs, CAFs, exosomes, and peripheral blood indicators, may have suggestive significance for tumor immune microenvironment and prognosis of immunotherapy." (PMID 36860322, 2023). "Even though these studies have not reported results selectively in an MTAP-negative tumour background, other clinical evidence is emerging that MTAP-negativity does not predict intra tumoral MTA accumulation as seen in model systems." (PMID 37795443, 2023).